LSP1 (lymphocyte specific protein 1)
Diseases named in the same sentence as LSP1 in open-access papers (continued):
Sharing a sentence is not in itself a finding about the gene and the disease.
keloid (2 papers, 2020 to 2025). An irregularly shaped, elevated mark on the skin caused by deposits of excessive amounts of collagen during wound healing. "Increased predicted expression of LSP1 in fibroblasts (p = 6.01 × 10-8, OR = 0.56 [0.46 – 0.69]) was associated with decreased risk of keloids." (PMID 40835838, 2025).
periodontitis (2 papers, 2021 to 2026). An acute or chronic inflammatory process that affects the tissues that surround and support the teeth. "In terms of the shared molecular mechanisms underlying periodontitis and renal cell carcinoma, six genes (IKZF1, LGALS1, LSP1, MNDA, VIM and WAS) were consistently upregulated in both disease tissues, indicating their potential involvement in the common pathogenesis of the two diseases." (PMID 42157182, 2026). "Four biomarker crosstalk genes between periodontitis and VTE were also immune genes, i.e., LGALS1, LSP1, SAMSN1, and WIPF1." (PMID 34925639, 2021). "Four potential biomarker crosstalk genes were also immune genes, i.e., LGALS1, LSP1, SAMSN1, and WIPF1 between periodontitis and VTE." (PMID 34925639, 2021). "Similar as for LSP1, no studies reported the role of SAMSN1 in periodontitis or VTE, yet." (PMID 34925639, 2021).
acne (1 paper, 2021). An inflammatory process of the sebaceous glands which is characterized by comedones, nodules, papules and/or pustules on the skin. "A clinical trial investigating oral supplementation of L. rhamnosus SP1 (LSP1) had been reported to bring health benefits to the patients such as LSP1 normalized skin expression of genes involved in insulin signalling and an improvement in the appearance of adult acne." (PMID 34680552, 2021).
atherosclerosis (1 paper, 2025). A disease characterized by the build-up of fatty material and calcium deposition in the arterial wall resulting in partial or complete occlusion of the arterial lumen. "We identified 12 lactylation-related genes that are more reliably associated with atherosclerosis: five upregulated genes (LSP1, IKZF1, MNDA, RCC2, and WAS) and seven downregulated genes (CSRP2, PPP1CB, CSRP1, HEXIM1, CALD1, PDLIM1, and RANBP2)." (PMID 40248193, 2025).
autoimmune disease (1 paper, 2023). A disorder resulting from loss of function or tissue destruction of an organ or multiple organs, arising from humoral or cellular immune responses of the individual to their own tissue constituents. "LSP1 is a negative regulator of leukocyte trafficking and activation, which has been replicated across multiple GWAS for BrCa incidence and outcome, as well as inflammatory and autoimmune diseases, yet the therapeutic potential of LSP1 is unknown." (PMID 37664640, 2023).
cervical cancer (1 paper, 2025). A primary or metastatic malignant neoplasm involving the cervix. "We focused on the specific associations between the presence of LSP1 and the infiltration of lymphocyte subtypes that are relevant to immunosuppression and anti-tumour activity in cervical cancer." (PMID 40038352, 2025). "We hypothesize that LSP1 expression may be associated with the stage of cervical cancer." (PMID 40038352, 2025). "The results demonstrated that LSP1 expression was significantly elevated in early-stage cervical cancer (Stage IB) but markedly decreased in advanced-stage cervical cancer (Stage IIIC)." (PMID 40038352, 2025). "The expression level of LSP1 in cervical tissue increases in the early stages of cervical cancer (CC), decreases with disease progression, and is positively associated with a favorable prognosis." (PMID 40038352, 2025). "Surprisingly, in contrast to the proteomics data, LSP1 exhibited higher expression levels in cervical cancer tissues compared to normal cervical tissues." (PMID 40038352, 2025). "To investigate this, we collected clinical tissue samples and performed immunohistochemistry (IHC) analysis, revealing increased LSP1 expression in cervical cancer tissues relative to normal cervical tissues, particularly in Stage IB cervical cancer." (PMID 40038352, 2025). "We detected that LSP1 was positively associated with both CD4+ and CT8+ T cell abundance in HPV16-positive cervical cancer." (PMID 40038352, 2025). "Future studies will further investigate the mechanisms and clinical significance of LSP1 in the activation of anti-tumor immunity in cervical cancer." (PMID 40038352, 2025). "The potential value of LSP1 as a novel target for staging and treatment stratification in cervical cancer warrants further investigation." (PMID 40038352, 2025). "Western blot and RT-qPCR analyses further confirmed these observations by demonstrating consistent protein and mRNA expression levels of LSP1 in early and advanced cervical cancer tissues." (PMID 40038352, 2025). "To further investigate this observation, we conducted Western blot and RT-qPCR analyses to evaluate the protein and mRNA expression levels of LSP1 in both early-stage and advanced-stage cervical cancer tissues." (PMID 40038352, 2025). "In addition, LSP1 was found to be distributed outside the cervical cancer cells, in cells existing in the tumour microenvironment (TME)." (PMID 40038352, 2025). "Notwithstanding the potential role of LSP1 as a tumour suppressor in cervical cancer, we are not able to claim any causal link of LSP1 expression to anti-tumour immunity in cervical cancer." (PMID 40038352, 2025). "This study suggests that LSP1 may serve as a valuable biomarker for determining the stage and prognosis of cervical cancer and is likely involved in the infiltration and activation of anti-tumor immune cells within the TME." (PMID 40038352, 2025). "Notably, LSP1 expression was higher in early-stage cervical cancer (Stage IB) than in advanced-stage disease (Stage IIIC)." (PMID 40038352, 2025). "In conjunction with existing knowledge, our results suggest that LSP1 might be tumour-suppressive in cervical cancer." (PMID 40038352, 2025). "Notably, LSP1 expression was lower in Stage IIIC cervical cancer tissues compared to Stage IB." (PMID 40038352, 2025). "Consistent with the IHC findings, LSP1 expression was higher in early-stage cervical cancer (Stage IB) compared to adjacent non-tumor tissues, while it was lower in advanced-stage cervical cancer (Stage IIIC)." (PMID 40038352, 2025). "Results indicated that both protein and mRNA levels of LSP1 were significantly elevated in cervical cancer tissues compared to adjacent non-tumor tissues." (PMID 40038352, 2025). "The mutual exclusion of LSP1 and TIM-3 expression on CD4+ and CD8+ T cells in the cervical cancer tissues examined in this study inferred that LSP1 and TIM-3 may exhibit counteracting effects on immune cells in TME." (PMID 40038352, 2025).
cervical cancer (continued). "Our interest in LSP1 was piqued by its significant reduction observed in patient samples positive for HPV16 infection, irrespective of the presence of cervical cancer, as demonstrated by proteomics data." (PMID 40038352, 2025).
cervical squamous cell carcinoma (1 paper, 2025). A squamous cell carcinoma arising from the cervical epithelium. "The results demonstrated that LSP1 expression was negatively correlated with cervical squamous cell carcinoma (CESC) tumor purity (r = − 0.351, p = 1.84e-09)." (PMID 40038352, 2025).
colon cancer (1 paper, 2020). "The effect of Lsp1 deficiency was reproduced in MC38 colon cancer." (PMID 33020243, 2020). "To explore whether the inhibitory effect of Lsp1 deficiency on tumor growth is reproduced in other types of solid tumor, we assessed the growth of MC38 colon cancer in WT and Lsp1 KO mice." (PMID 33020243, 2020).
diffuse large B-cell lymphoma (1 paper, 2007). "Interestingly, in diffuse large B-cell lymphoma (DLBL) LSP1 is also very much downregulated (GEO: GPL176 13667)." (PMID 17207284, 2007).
endothelial dysfunction (1 paper, 2024). In vascular diseases, endothelial dysfunction is a systemic pathological state of the endothelium (the inner lining of blood vessels) and can be broadly defined as an imbalance between vasodilating and vasoconstricting substances produced by (or acting on) the endothelium. "First, we investigated whether endothelial dysfunction in LSP1-KO mice is associated with eNOS instability, we immunoprecipitated native eNOS from aortae of the WT control mice and LSP1-KO mice followed by low-temperature (LT) SDS-PAGE to study the dimerization of eNOS in vivo." (PMID 38254711, 2024). "Although endothelial LSP1 has been previously studied in the context of inflammation and endothelial permeability, there has been a lack of information regarding the role of LSP1 in endothelial dysfunction, particularly the impact of LSP1 on endothelial hallmark molecule eNOS." (PMID 38254711, 2024).
hairy cell leukemia (1 paper, 2024). Hairy cell leukemia (HCL) is a rare type of leukemia in which abnormal B-lymphocytes are present in the bone marrow, spleen and peripheral blood. "The distinct morphological characteristics of hairy cell leukemia (HCL) cells can be attributed to the overexpression of pp52 (LSP1) and/or its specific association with the cytoskeleton." (PMID 38322112, 2024). "Elevated cytoskeleton-binding pp52 (LSP1) protein contributes to the distinctive morphology of hairy cell leukemia." (PMID 38322112, 2024).
Hepatic steatosis (1 paper, 2013). Steatosis is a term used to denote lipid accumulation within hepatocytes. "TLSP, LSP1, and LSP2 remarkably ameliorated hepatic lipid accumulation and ballooning degeneration and inhibited the progression of hepatic steatosis." (PMID 23762123, 2013).
insulinoma (1 paper, 2020). "Conversely, the significantly opposite methylation and expression changes exemplified by LSP1, H19, TH, KCNQ1, SLC22A18, OSBPL5 are thus more likely random and unrelated to insulinoma pathogenesis." (PMID 33060578, 2020).
lymphoid tumours (1 paper, 2016). "The expression of Lsp1 has been shown to be of diagnostic value for some lymphoid tumours, such as Hodgkin's disease." (PMID 27555448, 2016).
metabolic syndrome (1 paper, 2013). A cluster of metabolic risk factors for CARDIOVASCULAR DISEASES and TYPE 2 DIABETES MELLITUS. "The findings provide convincing evidences that small molecule polysaccharides (LSP1 and LSP2) may be a promising therapy for the treatment of type 2 diabetes mellitus and some related metabolic syndromes." (PMID 23762123, 2013).
Parkinson disease (1 paper, 2023). A progressive degenerative disorder of the central nervous system characterized by loss of dopamine producing neurons in the substantia nigra and the presence of Lewy bodies in the substantia nigra and locus coeruleus. "An increased level of LSP1 mRNA expression in blood was described recently as a potential diagnostic biomarker for Parkinson’s disease." (PMID 37047799, 2023).
primary immunodeficiency (1 paper, 2020). "The result of KEGG pathway analysis showed that LSP1 was significantly correlated to immune related pathways, such as leukocyte trans-endothelial migration, NF-kappa B signaling pathway, cytokine-cytokine receptor interaction, and primary immunodeficiency." (PMID 32003759, 2020).
resistant hypertension (1 paper, 2022). "Recently, SNPs near CASZ1, LSP1 and RXFP2 have been associated with resistant hypertension in a genome-wide association study of 14,756 patients from Iceland, the UK Biobank and eMERGE33." (PMID 36057693, 2022).
scrub typhus (1 paper, 2013). Scrub typhus is a rare dust mite-borne infectious disease caused by the Orientia tsutsugamushi bacterium and characterized clinically by an eruptive fever which is potentially serious. "Recently, a paper reported that O. tsutsugamushi mainly infects “inflammatory” CD14/LSP-1/CD68 positive monocytes and CD1a/DCSIGN/S100/FXIIIa and CD163 positive dendritic cells in stained eschar skin biopsies from scrub typhus patients." (PMID 23301113, 2013).
Stroke (1 paper, 2023). Sudden impairment of blood flow to a part of the brain due to occlusion or rupture of an artery to the brain. "Stroke has not yet been directly related to LSP1, but an association with LSP1 has been demonstrated for blood pressure, which is one of the most important risk factors of stroke." (PMID 37047799, 2023).
viral infection (1 paper, 2017). "Furthermore, LSP1, being involved in innate immunity, specifically neutrophil activation and chemotaxis, is another possible indicator of the involvement of viral infection in the pathogenesis of SS." (PMID 28122643, 2017).
tumor (21 papers, 2007 to 2025). "In previous studies, LSP1 was reported to be involved in immune escape, and LSP1 secreted by abnormally activated tumor cells regulates metastasis-associated macrophages." (PMID 38879666, 2024). "On the other hand, high expression of the caspase 8 (CASP8) and lymphocyte-specific protein 1 (LSP1) genes are associated with tumor inhibition in most cases." (PMID 33112566, 2020). "In this study, we postulated that Lsp1 deficiency promotes the antitumor activity of T cells by inducing cell migration and invasion into the tumor mass." (PMID 33020243, 2020). "LSP1 expression also had a close association with IDH1 wild type tumor, and could be used as an indicator for the survival of GBM patient with radio- and chemotherapy." (PMID 32003759, 2020). "This suggests that the reduced LSP1 expression in advanced-stage tumors may be associated with an exhausted T cell phenotype or a more pronounced inhibitory phenotype of regulatory T cells (Tregs) within the tumor microenvironment (TME)." (PMID 40038352, 2025). "Using the TISIDB database, we created a heatmap to analyse the detailed correlation between LSP1 and TILs in common tumours." (PMID 40038352, 2025). "This suggests that FCGR1A promotes tumor invasion by regulating LSP1, making it possible for FCGR1A to promote metastasis by modulating the function of immune cells in the peritoneal microenvironment." (PMID 38879666, 2024). "We orthogonally replicated the iTME-specific associations of LSP1 and TLR1 to BrCa risk using patient tumor biopsies and comparative mapping, respectively." (PMID 37664640, 2023). "The result showed that benign tissue around LSP1 high tumor had a significant lower LSP1 expression level than tumor tissue." (PMID 32003759, 2020). "Taken together, we believe that at least two possible mechanisms contribute to LSP1 regulation of tumor growth: 1) altered migration and infiltration of T cells into the tumor and 2) changes in the production of antitumor effector cytokines by CD8+ T cells." (PMID 33020243, 2020). "In sharp contrast with Lsp1 KO mice, Lsp1 Tg mice showed substantial acceleration of tumor growth over a period of 3 weeks in comparison to WT mice." (PMID 33020243, 2020). "Here, we provide novel mechanisms of LSP1 regulation of tumor growth and T cell infiltration in the TME." (PMID 33020243, 2020). "To this end, we measured the expression levels of IFN-γ and TNF-α, representative antitumor effector cytokines, 33 in splenic and tumor-infiltrating T cells in WT and Lsp1 KO mice by flow cytometry." (PMID 33020243, 2020). "In tumor tissue, Lsp1-overexpressing CD4+ and CD8+ T cells also showed markedly reduced frequencies of TNF-α+ and/or IFN-γ+ cells compared with WT CD4+ and CD8+ T cells, respectively." (PMID 33020243, 2020). "To better understand how the upregulation of LSP1 expression occurs in tumor-infiltrating T cells in vivo, we investigated which kinds of tumor-associated stimuli can induce LSP1 expression." (PMID 33020243, 2020). "Conversely, the frequencies of TNF-α+ and/or IFN-γ+ cells in splenic CD4+ and CD8+ cells were significantly lower in Lsp1 Tg mice than in WT mice after tumor inoculation." (PMID 33020243, 2020). "At day 14 after tumor inoculation, the volume and weight of the tumors derived from Lsp1 Tg mice were also significantly higher than those of WT mice." (PMID 33020243, 2020). "To extend our understanding of the T cell-specific effects of LSP1 during tumor development, we generated transgenic (Tg) mice that specifically overexpress Lsp1 in T cells using CD2 promoter, as described in ‘Materials and methods’ section." (PMID 33020243, 2020).